ACHE (acetylcholinesterase (Yt blood group))
Diseases named in the same sentence as ACHE in open-access papers (continued):
Sharing a sentence is not in itself a finding about the gene and the disease.
progeria (1 paper, 2018). "Induced progeria in young rats following chronic DHT administration significantly decreased the AChE activity in young and old erythrocytes of DHT-treated rats similar to naturally aged rats in comparison to corresponding young control rats." (PMID 30003010, 2018).
progressive supranuclear palsy (1 paper, 2016). A rare late-onset neurodegenerative disease characterized by supranuclear gaze palsy, postural instability, progressive rigidity, and mild dementia. "Cortical AChE activity differs between patients with PD and those with progressive supranuclear palsy (PSP)." (PMID 26984612, 2016).
ptosis (1 paper, 2020). The drooping of the upper eyelid. "This may be the reason why the ptosis which is observed in victims of Naja bite does not always respond to ASV and has to be treated with neostigmine, an AChE inhibitor." (PMID 33083200, 2020).
retinal degeneration (1 paper, 2018). Degeneration of the retina. "In order to test the effects of ATF3 on AChE, in vivo, we chose the mouse model of photic-stress-induced retinal degeneration, which we previously used to show the upregulation of AChE in photoreceptors apoptosis." (PMID 29681794, 2018). "In the rodent model of light-induced retinal degeneration, damage is restricted to the photoreceptors (ONL) where AChE expression is upregulated during photic-stress." (PMID 29681794, 2018).
sarcopenia (1 paper, 2021). Progressive decline in muscle mass due to aging which results in decreased functional capacity of muscles. "Rather, adverse side effects of AChE inhibitors include fatigue and muscle cramp, pointing to a possible exacerbation of sarcopenia symptoms." (PMID 34573265, 2021). "An important question emerging from this new evidence is whether acetylcholinesterase (AChE) inhibitors, that act to enhance cholinergic transmission, can ameliorate sarcopenia symptoms in AD." (PMID 34573265, 2021).
scrapie (1 paper, 2015). A fatal disease of the nervous system in sheep and goats, characterized by pruritus, debility, and locomotor incoordination. "It remains to be investigated whether AChE is present in scrapie-associated fibrils." (PMID 25853328, 2015). "To investigate whether this phenomenon occurs in vitro in cultured cells, we examined AChE protein level and enzymatic activity in the neuroglial mouse cell line MOVS6 that is persistently infected with the 127S scrapie strain, which phenotypically resembles LA21K fast prions." (PMID 25853328, 2015).
secondary hyperparathyroidism (1 paper, 2013). Overproduction of parathyroid hormone in response to influence external to the parathyroid glands. "Vitamin D might affect cognition at least partly independent of AChE and BuChE involving L-type voltage-sensitive calcium channels, nerve growth factor, prostaglandins, cyclooxygenase 2, reactive oxygen species, nitric oxide synthase, and prevention of secondary hyperparathyroidism." (PMID 24312390, 2013).
Seizure (1 paper, 2019). A seizure is an intermittent abnormality of nervous system physiology characterized by a transient occurrence of signs and/or symptoms due to abnormal excessive or synchronous neuronal activity in the brain. "Therefore, it was important to assess the levels of AChE in the hippocampus of the tested animals following PLC-induced seizures and SE." (PMID 31739417, 2019).
Sensory axonal neuropathy (1 paper, 2025). An axonal neuropathy of peripheral sensory nerves. "Enzyme Inhibition and Activation: Inhibition of AChE and activation of CYP2E1 result in sensory axonal neuropathy and increased mortality." (PMID 40332597, 2025).
sexual dysfunction (1 paper, 2023). Disturbances in sexual desire and the psychophysiologic changes that characterize the sexual response cycle and cause marked distress and interpersonal difficulty. "Additionally, the observed decrease in AChE could account for the BPF-induced sexual dysfunction." (PMID 37872365, 2023).
Sicca syndrome (1 paper, 2011). "In accordance, we show that salivary gland biopsies from SjS patients display higher levels of AChE compared to Sicca syndrome controls." (PMID 22174879, 2011).
Splenomegaly (1 paper, 2022). Abnormal increased size of the spleen. "To determine whether galantamine’s effect on splenomegaly is mediated by its AChE inhibitory activity, we treated FMF-KI mice with huperzine A, a potent centrally- and peripherally-acting AchE inhibitor that is structurally different from galantamine." (PMID 36494621, 2022).
substance abuse (1 paper, 2020). The use of a drug for a reason other than which it was intended or in a manner or in quantities other than directed. "There have not been many studies investigating the role of AChE gene and single nucleotide polymorphism (SNPs) for a molecular and genetics insight into mechanisms and possible predisposition towards addiction and substance abuse." (PMID 32414087, 2020).
supraglottis (1 paper, 2015). "In addition, the decreased AChE-T mRNA level in glottis-located tumours and its increased level in supraglottis tumours made unlikely AChE-T mRNA as the leading transcript for AChE activity in unaffected and cancerous pieces." (PMID 25956553, 2015).
Syncope (1 paper, 2019). A transient loss of consciousness (i.e., characterized by a rapid onset, a short duration, and a spontaneous and complete recovery) due to cerebral hypoperfusion. "Finally, the combination of M2R overexpression and incomplete compensation by AchE overexpression might be the mechanism behind reflex syncope, particularly the very severe equivalent of reflex syncope in infants." (PMID 31318899, 2019).
synucleinopathies (1 paper, 2025). "Prescriptions in patients with low suspicion for AD may be partially explained by the use of AchE inhibitors in synucleinopathies, e.g., DLB." (PMID 41231363, 2025).
temporal lobe epilepsy (1 paper, 2022). A localization-related (focal) form of epilepsy characterized by recurrent seizures that arise from foci within the temporal lobe, most commonly from its mesial aspect. "The BLA was chosen as the CNS site of interest because it receives dense cholinergic innervation, is rich in expression of AChE, is often a focal point for seizures in patients with temporal lobe epilepsy, and because it has been directly implicated in seizures as produced by OP-poisoning." (PMID 36479275, 2022). "We chose the basolateral amygdala (BLA) as the central location for these studies because it receives dense cholinergic innervation from the basal forebrain, is rich in expression of AChE, and is often a focal point for seizures in patients with temporal lobe epilepsy." (PMID 36479275, 2022).
thymoma (1 paper, 2008). A neoplasm arising from the epithelial cells of the thymus. "In-depth analysis of the expression levels of all ACHE probe-sets (core, extended and full) in MG-thymoma yielded two potentially new exons." (PMID 18545673, 2008).
Tinnitus (1 paper, 2018). Tinnitus is an auditory perception that can be described as the experience of sound, in the ear or in the head, in the absence of external acoustic stimulation. "AChE inhibitors might suppress presbycusis accompanied by tinnitus and may indirectly protect auditory and cognitive function by activating α7nAChR-mediated anti-inflammatory effects in various cells of the brain’s neural vascular unit." (PMID 29681847, 2018).
Tourette syndrome (1 paper, 2014). A neurologic disorder caused by defective metabolism of the neurotransmitters in the brain. "AChE inhibitors are also under investigation for the treatment of methamphetamine addiction and motor tics in Tourette syndrome." (PMID 24904300, 2014).
tularemia (1 paper, 2012). Tularemia is an infection caused by the bacterium Francisella tularensis. "Drugs based on AChE inhibition should be restricted when tularemia or disease with a similar pathogenesis is suspected." (PMID 22783145, 2012). "Administration of AChE inhibitors to individuals suffering from tularemia is contraindicatory." (PMID 22783145, 2012). "Administration of AChE inhibitors to the individuals suffering from tularemia is contra-indicatory." (PMID 22783145, 2012). "Drugs based on AChE should be restricted when tularemia is suspected." (PMID 22783145, 2012). "The hypothesis set in the experiment was based on the question whether administration of compounds directly stimulating nAChR, Ach in the presaent study, or compounds inhibiting AChE, represented by neostigmine, and thus elevating endogenous blood ACh level, could modulate tularemia progression." (PMID 22783145, 2012). "CAP is hypothesized to be able to modify tularemia progression on administration of either ACh as direct stimulator of nAChR or of the reversible acetylcholinesterase (AChE) inhibitor neostigmine, which protects endogenous ACh from splitting by blood AChE." (PMID 22783145, 2012). "Drugs based on AChE inhibition or nAChR stimulation are not applicable to individuals suspected to suffer from tularemia." (PMID 22783145, 2012).
urinary schistosomiasis (1 paper, 2017). A bladder infection that occurs as a manifetation of a systemic infection with one or more species of the parasitic worms of the Schistosoma type; this can progress to bladder cancer in time. "Targeting schistosome AChE, metrifonate was used historically as an effective drug for the treatment of urinary schistosomiasis, strongly emphasising the important role of the enzyme in the neuromuscular or cholinergic systems." (PMID 28906438, 2017).
α-dystroglycanopathies (1 paper, 2018). "Because perlecan-null mice show complete absence of AChE at the NMJ, it is possible that neuromuscular transmission in α-dystroglycanopathies may also be impaired by a disruption of an AChE-perlecan-αDG complex." (PMID 30578246, 2018).
neurodegenerative disease (173 papers, 2008 to 2026). A disorder of the central nervous system characterized by gradual and progressive loss of neural tissue and neurologic function. "While AChE inhibition is commonly associated with neurotoxicity, it is also a known therapeutic target in neurodegenerative diseases, suggesting concentration-dependent dual effects." (PMID 40807427, 2025). "Elevated levels of AChE result in depleted levels of acetylcholine at the synaptic cleft, a phenomenon implicated in the pathophysiology of memory loss observed in neurodegenerative diseases." (PMID 41438191, 2025). "Dysregulation of AChE activity is linked to neurodegenerative diseases like Alzheimer’s and is targeted therapeutically with AChE inhibitors to enhance cholinergic function." (PMID 39860136, 2025). "The activity in the enzyme inhibitions of the respective fractions were investigated for AChE, BChE, and tyrosinase, all brain enzymes that are associated with neurodegenerative diseases." (PMID 39771015, 2024). "The ability of flavonoids to target multiple pathogenic pathways, such as AChE inhibition, oxidative stress reduction, and neuroinflammation modulation, suggests their potential as complementary treatments for neurodegenerative diseases." (PMID 39796512, 2024). "Loss of brain AChE activity is evident in several brain disorders including neurodegenerative diseases as AD where the decrease of AChE in the cortex and hippocampus has been extensively reported." (PMID 36449200, 2023). "Alzheimer’s disease (AD) is a type of neurodegenerative disease, associated with the hastening of ROS, acetylcholinesterase (AChE) activity, and amyloid β peptides plaques in the brain." (PMID 37234712, 2023). "AChE is an important regulator and executor of apoptosis in mammalian cells and altered presence of AChE is associated with various degenerative diseases and cancer." (PMID 36329181, 2022). "Altered presence and functions of AChE are associated with various degenerative diseases including Alzheimer’s disease, Parkinson’s disease and cancer in various tissues." (PMID 36329181, 2022). "Neurodegenerative diseases are often associated with the cholinergic system, in which the main neurotransmitter is ACh, broken down by AChE." (PMID 34502198, 2021). "In regard to methylated xanthines, it was shown that caffeine can inhibit the activity of AChE and is therefore linked to a neuroprotective effect in neurodegenerative diseases like AD." (PMID 33260941, 2020). "Recent studies have found that AChE increased its activity is a major cause of neurodegenerative diseases." (PMID 30050927, 2018). "The literature suggests that the pathogenesis and central toxicity progression of multiple neurodegenerative diseases are associated with abnormal levels of AChE and MAO (Patlolla A K, Tchounwou 2005; Huot and Fox S H, Brotchie 2016; Nasr and El-demerdash F M, El-nagar W 2016)." (PMID 38771510, 2024). "Abnormal acetylcholinesterase (AChE) expression is intimately associated with a number of neurodegenerative diseases, as the elevated AChE enzyme activity leads to a decrease in acetylcholine (Ach) levels and subsequently the fast termination of nerve impulses and neural loss." (PMID 37291560, 2023). "The subacute IMI exposure can cause toxic effects, which can lead to a variety of neurodegenerative diseases, depending on the dose which its outcomes AChE inhibition; changes in antioxidant status caused by increased lipid peroxidation and a decrease in GSH, CAT, and SOD." (PMID 37727350, 2023). "However, high concentration of AChE decreased ACh level and was implicated in some neurodegenerative diseases including AD." (PMID 25045391, 2014). "The efficient and rapid discovery and screening of AChE inhibitors hold urgent and significant value for chemical toxin detection, toxicological research, and drug development for neurodegenerative diseases." (PMID 41836758, 2026).
neurodegenerative disease (continued). "Acetylcholine (ACh), acetylcholinesterase enzyme (AChE), and AChE inhibition are of great importance in the treatment of neurodegenerative diseases." (PMID 42037743, 2026). "AChE has been investigated for a long time as therapeutic target, following the discovery that it is involved in neurodegenerative diseases." (PMID 40123150, 2025). "Synthetic AChE inhibitors are commonly used to treat neurodegenerative diseases, and the present study suggests the potential usefulness of M. esculenta extracts." (PMID 39865641, 2025). "Its extratherapeutic potential for the treatment of neurodegenerative diseases is highlighted by its capacity to inhibit AChE and its suggested function in DHA transport to the brain, as reported in the literature." (PMID 40357902, 2025). "Higher AChE activity is anticipated to lower ACh levels and disrupt the cholinergic system, leading to neurodegenerative diseases." (PMID 39878784, 2025). "Neurodegenerative diseases (ND), marked by progressive neuronal degeneration, often involve dysregulation of acetylcholinesterase (AChE), a key enzyme in cholinergic neurotransmission." (PMID 40952625, 2025). "In this study, the potential of NSAIDs to modulate humanacetylcholinesterase (AChE), a key enzyme linking neuroinflammation,metabolic dysfunction and degenerative diseases, was evaluated." (PMID 41322614, 2025). "AChE is a key enzyme responsible for Ach degradation and is often elevated in neurodegenerative diseases." (PMID 40772264, 2025). "The pathogenesis of neurodegenerative diseases involves several mechanisms, including an altered activity of AChE, leading to inflammation, apoptosis, and oxidative stress." (PMID 39865641, 2025). "This activity is particularly relevant in the context of neurodegenerative diseases such as Alzheimer’s disease, where the inhibition of acetylcholinesterase (AChE) is a common therapeutic strategy." (PMID 39858504, 2025). "These advances have facilitated the exploration of multitarget hybrid structures, which not only inhibit AChE but also possess antioxidant or anti-inflammatory properties, opening new therapeutic avenues for neurodegenerative diseases." (PMID 40332446, 2025). "Molecular docking analysis indicated strong binding affinities between LOEO compounds and AChE, supporting its therapeutic potential for neurodegenerative diseases like Alzheimer’s." (PMID 40286153, 2025). "In a first study published in 2022 they developed a small library of cinnamic acid‐inspired photoswitchable multitarget inhibitors targeting both AChE and monoamine oxidase B (MAO‐B), both implicated in neurodegenerative diseases." (PMID 40123150, 2025). "A growing number of studies suggest that mushroom-derived substances can act synergistically with drugs used to treat neurodegenerative diseases, such as AChE inhibitors, anti-inflammatory agents, and antioxidants." (PMID 40807333, 2025). "Marine fungi have shown significant potential as sources of anticholinesterase compounds, which are crucial for treating neurodegenerative diseases like AD by inhibiting AChE and enhancing cholinergic transmission." (PMID 41295407, 2025). "In terms of biological activity, LOEO demonstrated potent acetylcholinesterase (AChE)-inhibitory activity, which is crucial in the context of treatments for neurodegenerative diseases such as Alzheimer’s." (PMID 40286153, 2025). "LOEO, rich in phenolic compounds such as carvacrol and thymol, has shown significant potential for inhibiting AChE, a crucial enzyme in the pathogenesis of neurodegenerative diseases." (PMID 40286153, 2025). "AChE inhibitors play a pivotal role in delaying the progression of neurodegenerative diseases by preserving cholinergic signaling and slowing degenerative changes." (PMID 40807313, 2025).